DPCD (deleted in primary ciliary dyskinesia homolog (mouse))
Description:
May play a role in the formation or function of ciliated cells.
Synonyms: DKFZP566F084; RP11-529I10.4
Tractability: Antibody: its Gene Ontology location is reachable by antibodies, with medium confidence; the Human Protein Atlas places it where antibodies can reach. PROTAC: ubiquitination databases record sites on it; its protein half-life has been measured.
Gene: Protein-coding gene on chromosome 10 (101,570,560 to 101,609,664, forward strand). Ensembl gene ENSG00000166171.
Subcellular location (Human Protein Atlas): Nucleoplasm; Vesicles; Mitotic spindle; Plasma membrane; Primary cilium
Gene Ontology:
Molecular function: protein binding
Cellular component: nucleus
Genetic constraint (gnomAD): Loss-of-function variants: 18 observed, 24.94 expected, observed/expected ratio (o/e) 0.72, 90% interval 0.5 to 1.07. The upper end of that interval is the gene's LOEUF score, 1.07, which puts it in group 4 of 6, group 1 being the genes least tolerant of losing a copy. Missense variants: 200 observed, 258.63 expected, observed/expected ratio (o/e) 0.77, 90% interval 0.69 to 0.87. Synonymous variants: 96 observed, 97.37 expected, observed/expected ratio (o/e) 0.99, 90% interval 0.83 to 1.17.
Homologues: Orthologues: chimpanzee DPCD (98% identical), macaque DPCD (97% identical), dog DPCD (91% identical), pig DPCD (91% identical), rabbit DPCD (90% identical), rat Dpcd (89% identical), guinea pig DPCD (89% identical), mouse Dpcd (88% identical), tropical clawed frog dpcd (66% identical), zebrafish dpcd (61% identical), Drosophila melanogaster CG13901 (39% identical).
Diseases named in the same sentence as DPCD in open-access papers:
DPCD is named in the same sentence as 1 disease in open-access papers, as found by Europe PMC text mining. Sharing a sentence is not in itself a finding about the gene and the disease. The quoted sentences say what the papers report.
Infertility (1 paper, 2023). "Some genes with lower expression levels, namely DPCD, NME8, and ENKUR, had not yet been clearly related to biological functions in sperm production, function, and/or infertility-related manifestations." (PMID 37174638, 2023).